FER1L4 (fer-1 like family member 4 (pseudogene))
Diseases named in the same sentence as FER1L4 in open-access papers (continued):
Sharing a sentence is not in itself a finding about the gene and the disease.
liver cancer (4 papers, 2021 to 2024). An epithelial or non-epithelial malignant neoplasm that arises from the liver. "The long non-coding RNA FER1L4, spanning 6.7 kilobases and situated at 20q11.22, has been associated with tumor proliferation, invasion, migration, and apoptosis in various cancers, including gliomas, oral squamous cell carcinoma, and liver cancer." (PMID 39039611, 2024). "For instance, FER1L4 played critical roles in multiple malignancies, including papillary thyroid cancer, colorectal cancer, liver cancer, oral squamous cell carcinoma." (PMID 36476264, 2023). "In conclusion, FER1L4 promotes drug-resistant liver cancer progression through the inhibition of the expressions of miR-106a and miR-372-5p, leading to the upregulation of E2F1 and the activation of NF-κB." (PMID 33868788, 2021). "After knocking down FER1L4 expression, the expressions of miR-106-5p and miR-372-5p were increased in the liver cancer cisplatin-resistant strains." (PMID 33868788, 2021). "Collectively, we provided solid evidence, through patient tissues and cell and animal models, that FER1L4 promoted liver cancer by downregulating miR-106a-5p and miR-372-5p, thus leading to an increased expression of E2F1 and NF-κB pathway." (PMID 33868788, 2021). "In this study, we sought to examine the potential role of FER1L4 in the progression of liver cancer." (PMID 33868788, 2021). "The results revealed that the expression of FER1L4 in liver cancer tissues was significantly increased compared with that of the adjacent tissues." (PMID 33868788, 2021). "For the purpose of investigating the relationship between FER1L4 and miR-106a-5p and between FER1L4 and miR-372-5p, we initially detected the expressions of miR-106a-5p and miR-372-5p in patients with liver cancer." (PMID 33868788, 2021). "We found that the expression of FER1L4 was increased, which consequently led to the progression of liver cancer." (PMID 33868788, 2021). "However, in liver cancer, overexpression of FER1L4 leads to DDP resistance, suggesting that the specific mechanism of FER1L4 in different cancers still needs to be explored." (PMID 39039611, 2024). "Another study revealed that FER1L4 predicts a good prognosis in liver cancer." (PMID 33868788, 2021). "In this study, fluorescence in situ hybridization (FISH) and quantitative reverse transcriptase polymerase chain reaction (qRT-PCR) assays were employed to explore the relationship between FER1L4 and the progression of liver cancer and the resistance of liver cancer cells." (PMID 33868788, 2021). "In addition, FER1L4 suppresses liver cancer proliferation and migration through phosphatidylinositol 3-kinase (PI3K)/protein kinase B (AKT) signal pathway." (PMID 33868788, 2021). "First, the expression of FER1L4 was increased in liver cancer tissues and cells." (PMID 33868788, 2021). "This study aimed at investigating the effects of Fer-1 like family member 4 (FER1L4) on chemotherapy resistance and liver cancer development by using clinically collected liver cancer tissues and commercially purchased human liver cancer cisplatin-resistant cell line HUH-7/DDP." (PMID 33868788, 2021). "Therefore, in this study, anti-Ago2 antibodies were used in RNA immunoprecipitation (RIP) experiments in liver cancer cisplatin-resistant cell extracts to determine whether FER1L4 and miR-106-5p/miR-372-5p belong to the same RISC." (PMID 33868788, 2021). "However, some previous studies have showed that FER1L4 may be a tumor suppressor in liver cancer." (PMID 33868788, 2021). "In conclusion, the results indicated that FER1L4 could inhibit the expression of miR-106a-5p/miR-372-5p, to activate E2F1-mediated NF-κB pathway, leading to drug resistance in liver cancer." (PMID 33868788, 2021).
liver cancer (continued). "Moreover, the expression of FER1L4 in liver cancer cell lines SK-HEP-1, Hep3B, and HUH-7 and HUH-7/DDP-resistant cell line was significantly increased compared with that of the normal liver cell line THLE-3, and among them, HUH-7/DDP-resistant strains had the highest expression of FER1L4." (PMID 33868788, 2021).
prostate carcinoma (4 papers, 2020 to 2025). A carcinoma that arises from epithelial cells of the prostate gland. "Depletion of FBXW7 abolished the cell proliferation inhibition caused by FER1L4 upregulation in prostate cancer cells, indicating that FER1L4 exerts antitumor activity through the miR-92a3p/FBXW7 axis." (PMID 40534867, 2025). "Depletion of FBXW7 abrogated inhibition of cell proliferation caused by upregulation of FER1L4 in prostate cancer cells, indicating that FER1L4 exerted antitumor activities via miR-92a-3p/FBXW7 axis." (PMID 35928868, 2022). "Higher expression of FER1L4 was associated with prostate cancer tissues of early stage (AJCC stage I/II)." (PMID 32140077, 2020). "Silencing of FBXW7 reversed the cell phenotypes caused by FER1L4 overexpression in prostate cancer cells." (PMID 32140077, 2020). "In addition, in contrast to low expression of FER1L4, the analysis of TCGA-PRAD dataset showed that miR-92a-3p was significantly upregulated in prostate cancer tissues (n = 495) compared with normal tissues (n = 52), indicating a potential regulatory association between miR-92a-3p and FER1L4." (PMID 32140077, 2020). "The expression of FER1L4 was higher in prostate cancer specimens from patients with early-stage prostate cancer." (PMID 40534867, 2025). "Upregulation of FER1L4 reduced proliferation and increased apoptosis of prostate cancer cells by sponging miR-92a-3p and upregulating FBXW7." (PMID 40534867, 2025). "The lower expression of lncRNA FER1L4 was observed in prostate cancer samples compared with normal prostate tissues." (PMID 35928868, 2022). "Early stage of prostate cancer patients had the higher expression of FER1L4 in prostate cancer specimens." (PMID 35928868, 2022). "The function role of FER1L4 was explored in prostate cancer cells by cell proliferation and cell apoptosis assays." (PMID 32140077, 2020). "The data demonstrated that the FER1L4/miR-92a-3p/FBXW7 axis controlled the key signaling pathway in prostate cancer cells." (PMID 32140077, 2020). "Our work provided new understandings for the regulation of YAP1 signaling by FER1L4/miR-92a-3p/FBXW7 axis in prostate cancer." (PMID 32140077, 2020). "Bioinformatic analysis, RNA pull down assay, western blotting and dual luciferase reporter assay were applied to study the molecular mechanism of FER1L4 in prostate cancer cells." (PMID 32140077, 2020). "The data demonstrated that FER1L4, a downregulated lncRNA in prostate cancer, was pivotal for cell proliferation and survival of prostate cancer." (PMID 32140077, 2020). "Overexpression of FER1L4 was performed to evaluate its role in prostate cancer cell proliferation and survival." (PMID 32140077, 2020). "As a positive regulator of FBXW7, we found that FER1L4 decreased stability of YAP1 protein to reduce its expression in prostate cancer cells." (PMID 32140077, 2020). "FER1L4 was significantly decreased in prostate cancer tissues (n = 492) compared with normal prostate tissues (n = 152)." (PMID 32140077, 2020). "Transfection of FER1L4 further revealed that FER1L4 inhibited cell proliferation and induced cell apoptosis in prostate cancer cells." (PMID 32140077, 2020). "The results revealed that FER1L4 control prostate cancer proliferation and apoptosis via upregulation of FBXW7 and downregulation of YAP1 and its target gene expression." (PMID 32140077, 2020). "In our collected specimens, RT-qPCR also showed that FER1L4 was downregulated in prostate cancer tissues (n = 78) compared with matched normal prostate tissues (n = 78)." (PMID 32140077, 2020). "Overexpression of FER1L4 inhibited cell proliferation and promoted cell apoptosis in prostate cancer cells." (PMID 32140077, 2020). "The activity of PI3K/AKT pathway was critical for survival and proliferation of prostate cancer and tightly regulated by FER1L4 in several cancer types." (PMID 32140077, 2020). "In conclusion, the study demonstrated a FER1L4/miR-92a-3p/FBXW7 axis in prostate cancer." (PMID 32140077, 2020).
prostate carcinoma (continued). "Additionally, the expression of FBXW7 was positively correlated with FER1L4 in prostate cancer tissues." (PMID 32140077, 2020). "It was found that FER1L4 was lower in prostate cancer tissues than normal tissues." (PMID 32140077, 2020). "In the present study, we firstly studied the role of FER1L4 in prostate cancer." (PMID 32140077, 2020). "The current findings introduced a pivotal role of FER1L4 in prostate cancer." (PMID 32140077, 2020). "We overexpressed FER1L4 in prostate cancer cells by transfection of pcDNA3-FER1L4." (PMID 32140077, 2020). "The current study aimed to investigate the role of FER1L4 in prostate cancer." (PMID 32140077, 2020). "Similar to its role in most other cancer types, FER1L4 was also downregulated in prostate cancer." (PMID 32140077, 2020). "The study provided new sights into understanding of the signaling network in prostate cancer and implied that FER1L4 might be a biomarker for patients with prostate cancer." (PMID 32140077, 2020). "Moreover, we found that FER1L4 expression was decreased in prostate cancer cells (PC-3, DU145, LNCaP) compared with the immortalized human prostatic epithelial cells (RWPE2)." (PMID 32140077, 2020). "The biological role and molecular mechanism of FER1L4 in prostate cancer is unknown." (PMID 32140077, 2020). "FER1L4 might be a biomarker and therapeutic target for patients with prostate cancer." (PMID 32140077, 2020). "Thus, the current study revealed a FER1L4/miR-92a-3p/FBXW7 axis in prostate cancer." (PMID 32140077, 2020). "Interestingly, in PC-3 and DU145 cells, we also observed that FER1L4 overexpression decreased the phosphorylation of AKT protein which was reversed towards FBXW7 silencing, indicating PI3K/AKT signaling was also regulated by FER1L4/FBXW7 in prostate cancer cells." (PMID 32140077, 2020).
clear-cell renal-cell carcinoma (3 papers, 2020 to 2022). "Our work presents a comprehensive expression analysis of Fer1L4 in clear-cell renal-cell carcinoma and its influence on clinicopathological parameters and survival highlighting the role of Fer1L4 as a prognostic tissue biomarker." (PMID 31965534, 2020). "At present, little is known about the role in tumor biology of the lncRNA Fer-1 like family member 4 (Fer1L4) in clear-cell renal-cell carcinoma (ccRCC)." (PMID 31965534, 2020).
colorectal cancer (2 papers, 2022 to 2023). A primary or metastatic malignant neoplasm that affects the colon or rectum. "FER1L4 expression was associated with RB1 expression in colorectal cancer patients." (PMID 35928868, 2022). "In colorectal cancer patients, FER1L4 expression levels were downregulated, while RB1 expression was upregulated." (PMID 35928868, 2022). "FER1L4 sponged miR-1273g-3p and increased the expression of PTEN and led to cell cycle arrest and metastasis suppression in colorectal cancer." (PMID 35928868, 2022).
metastatic tumors (2 papers, 2020). "Increased expression significantly correlates with tumor aggressiveness: high expression levels of Fer1L4 RNA were found in higher grade, higher stage, and metastatic tumors." (PMID 31965534, 2020). "For example, lncRNA Fer1L4 was overexpressed in ccRCC tissues, and its high expression levels were found in higher grade, higher stage, and metastatic tumors." (PMID 33088626, 2020).
oral squamous cell carcinoma (2 papers, 2023 to 2024). "For instance, in oral squamous cell carcinoma, FER1L4 exhibits elevated expression and functions as a carcinogen by targeting the miR-133a-5p/Prx1 axis, thereby enhancing cancer cell viability and diminishing overall patient survival." (PMID 39039611, 2024).
pancreatic adenocarcinoma (2 papers, 2019 to 2023). "Next, stage expression analysis for the 20 RNAs was conducted in pancreatic adenocarcinoma by GEPIA database, and three RNAs (RP11-719K4.3, FER1L4 and AK4P1) were selected for subsequent study." (PMID 36476264, 2023).
papillary thyroid cancer (2 papers, 2021 to 2023). "In conclusion, these results suggested there may exist an axis between FER1L4, miR-612, and CDH4 which involves the tumorigenesis and aggressiveness of papillary thyroid cancer." (PMID 34289835, 2021).
autoimmune disease (1 paper, 2025). A disorder resulting from loss of function or tissue destruction of an organ or multiple organs, arising from humoral or cellular immune responses of the individual to their own tissue constituents. "Genes such as DBH, WDR62, NRG1, and FER1L4, identified in hepatic and blood immune transcriptomes, were also implicated in a broad range of disorders, including major depressive disorder, autoimmune diseases, and cancer, which have been previously associated with hepatitis." (PMID 41347690, 2025).
colorectal tumors (1 paper, 2017). "Similarly, previous studies have also found an association between higher expression levels of FER1L4 and tumor suppressor functions, and between up-regulation of the miR-135b and BST2 genes and both metastatic and poor prognosis colorectal tumors." (PMID 29296198, 2017).
esophageal squamous cell carcinoma (1 paper, 2020). Esophageal squamous cell carcinoma (ESCC) is a type of esophageal carcinoma (EC) that can affect any part of the esophagus, but is usually located in the upper or middle third. "FER1L4 also repressed esophageal squamous cell carcinoma proliferation." (PMID 32140077, 2020).
glioblastoma (1 paper, 2020). The most malignant astrocytic tumor (WHO grade IV). "Additionally, siRNA-mediated knockdown of Fer1L4 decreased invasiveness of glioblastoma cells and induced apoptosis." (PMID 31965534, 2020).
lymph node metastasis (1 paper, 2021). "Upregulated expression of FER1L4 in PTC tissues was positively correlated with lymph node metastasis (P = 0.020), extrathyroidal extension (P = 0.013) and advanced TNM stages (P = 0.013)." (PMID 34289835, 2021).
melanoma (1 paper, 2024). A malignant, usually aggressive tumor composed of atypical, neoplastic melanocytes. "Our results, for the first time, clearly showed the association of the FER1L4 pseudogene with melanoma and with favorable immune profiles, as well as better patient survival." (PMID 39764216, 2024). "This is the first study to demonstrate the association of FER1L4 with melanoma." (PMID 39764216, 2024). "Our study demonstrated that the FER1L4 is upregulated in melanocytes and various melanoma cell lines, with expression levels correlated with BRAF mutations, particularly the BRAF V600E variant." (PMID 39764216, 2024). "Then, the FER1L4 pseudogene was examined in melanoma patients using TCGA data and showed significant differences in expression between primary and metastatic samples (0.229 vs. 0.599; p = 2.43 x 10-6)." (PMID 39764216, 2024). "Expression of the FER1L4 was significantly upregulated in melanoma cell lines compared to normal melanocytes (1.091 x 10-5 ± 1.090 x 10-5 vs. 0.004901 ± 0.002654; p = 0.0034)." (PMID 39764216, 2024). "The activation of the STAT pathway was observed in melanoma patients with higher expression of the FER1L4 compared to the patients with lower levels of this pseudogene." (PMID 39764216, 2024). "In this study, we observed that FER1L4 possesses bidding sites and is negatively correlated with three miRNAs named miR-514a-5p, miR-330-5p, and miR-128-3p in melanoma patients." (PMID 39764216, 2024). "This study focuses on evaluating the FER1L4 pseudogene and its potential role in melanoma." (PMID 39764216, 2024). "FER1L4 expression was analyzed in normal melanocytes and melanoma cell lines using qRT-PCR." (PMID 39764216, 2024). "In vitro analysis revealed significant upregulation of FER1L4 in melanoma cells." (PMID 39764216, 2024). "This work is focused on the analysis of FER1L4 (Fer-1 like family member 4 pseudogene; named also as C20orf124) transcript in human primary epidermal melanocytes and melanoma cell lines with different BRAF mutation status, as well as in melanoma patients based on the TCGA dataset." (PMID 39764216, 2024). "Therefore, the FER1L4 may serve as a valuable biomarker in melanoma." (PMID 39764216, 2024). "The expression levels of the FER1L4 in normal melanocytes - HEMa and HEMn (BRAF WT) cell lines, and human melanoma cell lines MEWO (BRAF WT), SKMEL28, WM9, A375 (BRAF V600E), WM115, and WM266 (BRAF V600D) were measured using qRT-PCR." (PMID 39764216, 2024). "To date, the FER1L4 expression in melanoma has not been reported." (PMID 39764216, 2024).
metastatic melanoma (1 paper, 2024). A melanoma that has spread from its primary site to another anatomic site. "It was noted that the FER1L4 pseudogene levels were significantly upregulated in metastatic melanoma tissues, and its expression was associated with patient survival and immune profiles." (PMID 39764216, 2024).
prostate tumors (1 paper, 2020). "The lncRNA Fer-1-like protein 4 (FER1L4) expression was explored in prostate tumors and normal prostate tissues by RT-qPCR and bioinformatic analysis." (PMID 32140077, 2020). "The expression of FER1L4 was detected in prostate tumors and matched normal tissues." (PMID 32140077, 2020).
renal carcinoma (1 paper, 2022). A carcinoma arising from the epithelium of the renal parenchyma or the renal pelvis. "Furthermore, FER1L4 was reported to be an oncogenic and adverse prognostic marker in pancancer, renal cancer and glioma." (PMID 36272991, 2022).
renal cell carcinoma (1 paper, 2020). "In the absence of any data regarding to the role of Fer1L4 in renal-cell carcinoma (RCC), our study was designed to explore the expression pattern of Fer1L4 in RCC and corresponding normal tissues to investigate its influence on tumor biology and impact on patients’ survival." (PMID 31965534, 2020).
rheumatoid arthritis (1 paper, 2021). A chronic, systemic autoimmune disorder characterized by inflammation in the synovial membranes and articular surfaces. "In addition, FER1L4 regulates rheumatoid arthritis by modulating NLRC537." (PMID 34158566, 2021).
thyroid cancer (1 paper, 2021). "In this study, we observed preferential upregulation of lncRNA FER1L4 in thyroid cancer tissues (n = 513), compared with normal thyroid tissues (n = 58)." (PMID 34289835, 2021).